SPNS2 (SPNS lysolipid transporter 2, sphingosine-1-phosphate)
Diseases named in the same sentence as SPNS2 in open-access papers (continued):
Sharing a sentence is not in itself a finding about the gene and the disease.
triple-negative breast carcinoma (2 papers, 2025 to 2026). An invasive breast carcinoma which is negative for expression of estrogen receptor (ER), progesterone receptor (PR), and human epidermal growth factor receptor 2 (HER2). "GUSBP11 also enhances the expression of sphingolipid transporter 2 (SPNS2) in triple-negative breast cancer cell lines and suppresses the malignancy of triple-negative breast cancer cells by sponging miR-579-3p." (PMID 41431719, 2026).
acute kidney injury (1 paper, 2024). Sudden and sustained deterioration of the kidney function characterized by decreased glomerular filtration rate, increased serum creatinine or oliguria. "Organ-specific biomarkers, such as the Spns2/S1P axis in lung macrophages, mitochondrial dysfunction in the heart, proenkephalin for early acute kidney injury (AKI), and adrenomedullin for predicting multi-organ failure, offer promising avenues for timely intervention." (PMID 39594987, 2024).
acute myeloid leukemia (1 paper, 2021). Acute myeloid leukemia (AML) is a group of neoplasms arising from precursor cells committed to the myeloid cell-line differentiation. "In acute myeloid leukemia, SPNS2 is an indicator of poor prognosis; however, the effects of SPNS2 could potentially be neutralized by allogeneic hematopoietic stem cell transplantation (allo-HSCT)." (PMID 33673355, 2021).
Alzheimer disease (1 paper, 2021). A progressive, neurodegenerative disease characterized by loss of function and death of nerve cells in several areas of the brain leading to loss of cognitive function such as memory and language. "Spinster homolog 2 (Spns2), an S1P transporter, facilitates the proinflammatory activation of microglia in vitro and in vivo, contributing to accelerating the pathogenesis of Alzheimer's disease." (PMID 34992508, 2021).
breast tumor (1 paper, 2022). "Correlation analysis revealed that the level of SPNS2 were positively associated with SPHK1 levels in breast tumor tissues (***p < 0.0001)." (PMID 36309544, 2022).
cataract (1 paper, 2021). Partial or complete opacity of the crystalline lens of one or both eyes that decreases visual acuity and eventually results in blindness. "Spns2 knockout mice display reduced lymphocytes number together with hearing loss and cataracts." (PMID 34572307, 2021).
chronic obstructive pulmonary disease (1 paper, 2021). A chronic and progressive lung disorder characterized by the loss of elasticity of the bronchial tree and the air sacs, destruction of the air sacs wall, thickening of the bronchial wall, and mucous accumulation in the bronchial tree. "Tran HB and colleagues reported that Spns2 is reduced in bronchial epithelium of a mouse model of COPD (chronic obstructive pulmonary disease) compared to control animals with a strong positive correlation between Spns2 reduction and impairment of the phagocytic activity of macrophages." (PMID 34572307, 2021).
cognitive decline (1 paper, 2020). "Spns2 knockout mice display reduced inflammatory microglia phenotypes and Spns2 is possibly involved in the Aβ42-induced NF-κB signaling and cognitive decline." (PMID 33633739, 2020). "Spns2 knockout mice show reduced inflammatory microglia phenotypes, suggesting that S1P transport is important for the activation of microglia and provides evidence that S1P contributes to Aβ-induced NF-κB signaling and cognitive decline." (PMID 33633739, 2020).
colon adenocarcinoma (1 paper, 2021). "To further explore the impact of SPNS2 on CRC progression, we then analyzed the correlation between SPNS2 expression and the clinic pathological parameters of CRC patients in TCGA CRC datasets, including COAD (Colon adenocarcinoma) and READ (Rectum adenocarcinoma)." (PMID 34249729, 2021).
colon adenoma (1 paper, 2021). An adenoma that arises from the colon. "Our clinic-pathological study showed that SPNS2 expression in CRC was frequently lower than in colon adenomas, which were precursor lesions of CRC." (PMID 34249729, 2021). "In this study, we disclosed that SPNS2 expression, which was regulated by copy number variation and DNA methylation of its promoter, was dramatically upregulated in colon adenoma and CRC compared to normal tissues." (PMID 34249729, 2021). "However, we found that SPNS2 expression in CRC was lower than that in colon adenomas, which are precursor lesions of CRC, from analysis CRC datasets GSE4183, GSE89076, GSE41657, GSE34472 and GSE57965." (PMID 34249729, 2021). "Although its expression level was significantly lower in normal tissue than in CRC and colon adenoma, CRC possessed a dramatically lower SPNS2 expression than colon adenoma, suggesting a provoking role of SPNS2 in the early stage of CRC but an inhibiting role of it during CRC progression." (PMID 34249729, 2021).
COVID-19 (1 paper, 2020). A disease caused by infection with severe acute respiratory syndrome coronavirus 2. "On the other hand, the modulation of S1P release/content, through S1P transporter (i.e., Spns2), SphK and/or S1P lyase activities, and S1PR-mediated signaling may be important therapeutic approaches for COVID-19 because they might prevent SARS-CoV-2 infection or virus propagation." (PMID 32942748, 2020).
hepatitis B virus infection (1 paper, 2016). A viral infection caused by the hepatitis B virus. "Regarding the etiology of liver diseases, SPL and SPNS2 mRNA levels in liver were lower in the patients with hepatitis B virus infection than in those with other etiology (data not shown)." (PMID 27562371, 2016).
iron deficiency (1 paper, 2024). "The findings indicated that iron deficiency specifically upregulated the transcriptional activity of HIF1α and Sp1 on SPNS2, with Sp1 demonstrating a more pronounced increase in transcriptional activity compared to HIF1α." (PMID 39228402, 2024). "Treatment with PX478, an inhibitor of HIF1α, and Mithramycin A, an inhibitor of Sp1, resulted in a reversal of the upregulation of SPNS2 mRNA and protein expression caused by iron deficiency, with Mithramycin A exhibiting a more pronounced effect." (PMID 39228402, 2024).
liver diseases (1 paper, 2016). "Thirdly, SPL and SPNS2 mRNA levels in liver were lower in the patients with HBV infection than in those with other etiology in the present study, suggesting that it would be interesting to analyze the samples separately according to the etiology of liver diseases." (PMID 27562371, 2016).
lymph node metastasis (1 paper, 2021). "In the current study, univariate and multivariate analysis both identified SPNS2 expression, T status, lymph node metastasis, and histological grade as important independent prognosis factors affecting the overall survival of OSCC stage III/IV patients." (PMID 33673355, 2021). "Multivariate analysis identified SPNS2 expression, T status, lymph node metastasis and histological grade as independent prognostic indicators of the overall survival of OSCC stage III/IV patients." (PMID 33673355, 2021). "Univariate analysis identified SPNS2 expression, lymph node metastasis and histological grade as prognostic indicators of overall survival." (PMID 33673355, 2021). "Multivariate Cox proportional hazard models revealed that cytoplasmic SPNS2 expression, T status, lymph node metastasis, and histological grade were independent prognostic factors for survival." (PMID 33673355, 2021).
malaria (1 paper, 2021). Malaria is a serious and sometimes fatal disease caused by a parasite that commonly infects a certain type of mosquito which feeds on humans. "Furthermore, less than 2 kb upstream of malaria-associated SPNS2, the fourth-highest TR outlier, there are three variants within 36 bp of each other that have undergone three distinct allele frequency shifts in Africa, Asia, and Europe." (PMID 33185667, 2021).
melanoma (1 paper, 2020). A malignant, usually aggressive tumor composed of atypical, neoplastic melanocytes. "Indeed, the deletion of Spns2, either globally or in a lymphatic endothelial cell-specific manner, was associated with an increased ratio of effector T-cells to immunosuppressive Tregs, in the lungs of Spns2-deficient mice intravenously injected with B16F10 or HCmel12 murine melanoma cells." (PMID 32858889, 2020).
myocardial infarction (1 paper, 2021). Gross necrosis of the myocardium, as a result of interruption of the blood supply to the area, as in coronary thrombosis. "In a pathological setting of myocardial infarction, the bioactive peptide apelin enhances the secretion of S1P in lymphatic endothelial cells, by modulating the expression of Spns2 and SphK2." (PMID 34572307, 2021).
pancreatic cancer (1 paper, 2019). "A coexpression network revealed a hub comprising lncRNAs (MIR210HG, SNHG1, and LOC729970) and mRNAs (RAB3D, DDX17, and SPNS2) that presumably mediate drug resistance in pancreatic cancer." (PMID 31399552, 2019).
prostate carcinoma (1 paper, 2016). A carcinoma that arises from epithelial cells of the prostate gland. "In line with our recent data suggesting an autocrine effect of S1P in regulating HIF-1α in hypoxic prostate cancer cells, the silencing of Spns2 was associated with a significant inhibitory effect on HIF-2α accumulation under hypoxia in both CAKI-1 and A498 cells." (PMID 26974204, 2016).
renal fibrosis (1 paper, 2025). A final common manifestation of a wide variety of chronic kidney diseases characterized by glomerulosclerosis and tubulointerstitial fibrosis. "The importance of cellular S1P export is supported by the observation that blockade of SPNS2-mediated S1P export ameliorates renal fibrosis." (PMID 39899071, 2025).
retinal degeneration (1 paper, 2014). Degeneration of the retina. "We also found focal retinal degeneration in these mutant eyes suggesting a role for Spns2 in the photoreceptor and/or retinal pigment epithelium." (PMID 25356849, 2014). "We also found focal retinal degeneration and anomalies of retinal capillaries together with anterior eye defects in Spns2 mutant mice." (PMID 25356849, 2014).
Skin Cutaneous Melanoma (1 paper, 2021). "Moreover, its expression in metastasis SKCM (Skin Cutaneous Melanoma) was significantly lower than in primary SKCM, suggesting a general tumor suppressor role of SPNS2." (PMID 34249729, 2021).
tumor (20 papers, 2016 to 2025). "In contrast, recent data indicate an unexpected role for SPNS2 in metastasis and tumor-associated immunity." (PMID 35163211, 2022). "Being a S1P transporter, the levels of SPNS2 were found to be positively associated with SPHK1 expression in tumor tissue in the current study." (PMID 36309544, 2022). "A notable reduction in pulmonary metastasis in Spns2-deficient mice was linked to the inability of tumor cells to establish metastatic foci." (PMID 33673355, 2021). "To elucidate the underlying molecular mechanisms of SPNS2-mediated anti-tumor effect, we screened these four cancer pathways pathway activity assay using Cignal Reporter Assay Kits of QIAGEN, which measuring the activities of downstream transcription factors through dual-luciferase format." (PMID 34249729, 2021). "Two genes were upregulated (SERHL2 and SPNS2) in low cytoplasmic CAIX tumours, while one gene (PCSK1N) was downregulated, as shown in the volcano plot and MA plot (respectively)." (PMID 39660488, 2024). "The promotion of tumor progression by SPNS2 is facilitated through the regulation of tumor immunity and the enhancement of tumor cell migration and invasion." (PMID 39228402, 2024). "The levels of SPNS2 were found to be downregulated in tumor tissue as compared to adjacent normal tissue in TCGA cohort." (PMID 36309544, 2022). "Consistently, SPNS2 expression levels were lower in advanced T stages, which describes the size of the main tumor." (PMID 34249729, 2021). "On the other hand, SPNS2 can also promote tumor growth by transporting S1P to the extracellular environment." (PMID 33673355, 2021). "On the contrary, we found that SPNS2 was significantly downregulated in most types of tumors including LUAD and LUSC, which indicated the tumor suppressor function of SPNS2." (PMID 34249729, 2021). "On the other hand, in order to explore the potential functions and mechanisms of SPNS2 and its relationship with therapeutic drugs, it is necessary to further analyze the tumor suppressor function of SPNS2 in OSCC based on in vitro and in vivo experiments." (PMID 33673355, 2021). "Consistent with our results, previous studies have implicated SPNS2 in the development of OSCC and tumor progression." (PMID 33673355, 2021). "Apart from these results for SPNS2 in tumor cells, the most striking result highlights the importance of healthy tissue SPNS2 for metastasis." (PMID 31330821, 2019). "In addition, deletion of SPNS2 creates higher ratios of effector T cells and natural killer cells that can subsequently attack tumor cells and decrease metastatic burden." (PMID 37499662, 2023). "In summary, our data reveal that SPNS2 acts as a tumor suppressor during CRC progression." (PMID 34249729, 2021). "Our results indicate that SPNS2 may have tumor suppressor function in OSCC cells, which is consistent with previous reports." (PMID 33673355, 2021). "And SPNS2 can also promote the tumor growth via transporting S1P to extracellular environment." (PMID 32489475, 2020). "It is unclear why SPNS2 deficiency specifically affects the development of metastases but has no impact on primary tumor growth." (PMID 28209174, 2017). "They found host Spns2 plays a role in promoting metastasis via modulating lymphocyte trafficking, outlining Spns2 as a promising therapeutic target against tumor metastasis, which may take the place of existing S1P pathway interventions to overcome their broad side-effect." (PMID 28290052, 2017).
tumor (continued). "In skeletal muscles of animals bearing the C26 tumor, a well-known model of cancer cachexia, and in C2C12 myotubes treated with dexamethasone, a down-regulation of active SK1 was observed, while an up-regulation of Spns2 and S1P2 occurred." (PMID 33525436, 2021). "To explore the potential role and specific mechanism of SPNS2 in cancer progression, we assessed the expression profiles of SPNS2 in tumor and adjacent noncancerous tissues in TCGA datasets using the “DiffExp module” of TIMER." (PMID 34249729, 2021). "However, lacking of SPNS2 can reduce the ability of S1P to regulate lymphocyte transport, which leads to a decreased lymphocyte circulation in the tissue and increased in the proportion of T cells or NK cells, thereby killing tumor cells more effectively." (PMID 33673355, 2021). "In addition, silencing of SPNS2 increased MMP2 and MMP9 expression, while overexpression of SPNS2 decreased the MMP2 and MMP9 expression, which could degrade the extracellular matrix and stimulate tumor invasion and metastasis." (PMID 34249729, 2021).
cancer (17 papers, 2014 to 2024). A tumor composed of atypical neoplastic, often pleomorphic cells that invade other tissues. "Another transporter, Spinster homologue 2 (Spns2) is closely linked with the regulation of S1P levels to augment cancer cell survival, growth, proliferation, metastasis and chemoresistance." (PMID 32456134, 2020). "SPNS2, as a functional transporter of S1P, has been identified to be associated with many cancers." (PMID 32489475, 2020). "SPNS2 promoted cancer genesis, apoptosis and migration via S1P/S1PRs pathways that activated downstream signalling such as STAT3, AKT, ERK, Ras and Rac." (PMID 39660488, 2024). "There is an increasing body of evidence stating that Spns2 promotes cancer development, cell survival, and metastasis, mainly via increasing the extracellular S1P concentration, which results in the activation of S1PRs." (PMID 39595959, 2024). "In total, nine inflammation and cancer-associated DEGs were selected to show their changed expression patterns, comprising four up-DEGs (ADM, FSTL3, SPDEF, and SPNS2) and five down-DEGs (TACSTD2, CCL2, EDIL3, FAM20C, and OLFML2A)." (PMID 37953789, 2023). "Summarily, we identify LAPAS1 as a novel E2F-regulated lncRNA that has a potential role in human cancer and regulates cell-cycle progression and cell proliferation, at least in part, via regulation of SPNS2." (PMID 34084281, 2021). "S1P, a bioactive sphingolipid metabolite that involved in many physiology and pathology process including cancer genesis and progression, is the transport target of SPNS2." (PMID 34249729, 2021). "Sphingolipid Transporter 2 (SPNS2) is an S1P transporter that is best known for its roles in the survival and migration of cells, including cancer cells." (PMID 34084281, 2021). "It has been reported that SPNS2 generally showed a promoting effect in the genesis, apoptosis and migration of cancer, through S1P/S1PRs pathways activating downstream signaling such as AKT, STAT3, ERK, Ras and Rac." (PMID 34249729, 2021). "In addition, genetic polymorphism, somatic mutations, or other means of increased expression or activity of SPNS2 and other components of the S1P pathway may play a causal role in promoting cancer metastasis, which should be an important topic for future investigations." (PMID 28209174, 2017). "Future studies need to investigate these questions, and explore the therapeutic effect of S1P and SPNS2 inhibition in established metastasis, which more closely mimics the clinical situation of late-stage cancer patients." (PMID 28209174, 2017). "These contrasting results could be explained by the need of SPNS2–S1P signaling to stimulate specific or opposing S1P receptors in a cancer type-specific manner." (PMID 35565311, 2022). "Thus, we identify LAPAS1 as a new E2F-regulated lncRNA that has a potential role in human cancer and regulates cell proliferation and cell-cycle progression, at least in part, via regulation of SPNS2." (PMID 34084281, 2021). "Spinster homologue 2 (SPNS2), a transporter of S1P (sphingosine-1-phosphate), has been reported to mediate immune response, vascular development, and pathologic processes of diseases such as cancer via S1P signaling pathways." (PMID 34249729, 2021). "S1P can be secreted from cancer cells via specific transporters like protein spinster homolog 2 (SPNS2) and ABC transporters, of which the latter involve ABC sub-family A member 1 (ABCA1), ABC sub-family C member 1 (ABCC1), and ABC sub-family G member 2 (ABCG2)." (PMID 34820423, 2021). "al demonstrated that human SPNS2 can also transport S1P and its analogue, indicating SPNS2 may participate in the progress of cancer adjustment." (PMID 32489475, 2020). "As circulating S1P levels are tightly controlled by SPNS2, and increasing S1P levels with DOP treatment can suppress metastasis, S1P could be used as a biomarker of metastasis susceptibility in cancer patients." (PMID 28209174, 2017).